GALK1 (galactokinase 1)
Description:
Catalyzes the transfer of a phosphate from ATP to alpha-D-galactose and participates in the first committed step in the catabolism of galactose.
Synonyms: GALK; GK1; HEL-S-19
Tractability: Small molecule: a structure with a bound ligand is known; a high-quality ligand is known; it has a high-quality binding pocket; it belongs to a druggable protein family. PROTAC: ubiquitination databases record sites on it; its protein half-life has been measured; a small molecule that binds it is known.
Target class: Enzyme; Transferase
Chemical probes: ML152
Gene: Protein-coding gene on chromosome 17 (75,751,470 to 75,765,251, reverse strand). Ensembl gene ENSG00000108479.
Subcellular location (Human Protein Atlas): Cytosol; Golgi apparatus
Pathways (Reactome):
Disease: Defective GALK1 causes GALCT2
Metabolism: Galactose catabolism
Gene Ontology:
Molecular function: ATP binding; galactokinase activity; galactose binding; protein binding; kinase activity; phosphotransferase activity, alcohol group as acceptor
Biological process: galactose metabolic process; galactose catabolic process via UDP-galactose, Leloir pathway; carbohydrate phosphorylation
Cellular component: cytoplasm; extracellular exosome; membrane; cytosol
Genetic constraint (gnomAD): Loss-of-function variants: 30 observed, 33.97 expected, observed/expected ratio (o/e) 0.88, 90% interval 0.66 to 1.2. The upper end of that interval is the gene's LOEUF score, 1.2, which puts it in group 5 of 6, group 1 being the genes least tolerant of losing a copy. Missense variants: 512 observed, 513.15 expected, observed/expected ratio (o/e) 1, 90% interval 0.93 to 1.07. Synonymous variants: 240 observed, 222.38 expected, observed/expected ratio (o/e) 1.08, 90% interval 0.97 to 1.2.
Gene-disease validity (ClinGen):
ClinGen rates the evidence that GALK1 causes each of these diseases.
galactokinase deficiency (autosomal recessive): Definitive.
Homologues: Orthologues: chimpanzee GALK1 (100% identical), macaque GALK1 (93% identical), rabbit GALK1 (92% identical), dog GALK1 (91% identical), guinea pig GALK1 (90% identical), mouse Galk1 (88% identical), rat Galk1 (87% identical), pig GALK1 (85% identical), zebrafish galk1 (65% identical), tropical clawed frog galk1 (64% identical). Paralogues in human: GALK2 (34% identical), MVK (22% identical).
Diseases named in the same sentence as GALK1 in open-access papers:
GALK1 is named in the same sentence as 38 diseases in open-access papers, as found by Europe PMC text mining. Sharing a sentence is not in itself a finding about the gene and the disease. The quoted sentences say what the papers report.
galactosemia (20 papers, 2009 to 2025). "The situation in which NBS is used to detect other diseases for classic galactosemia is the same as that for GALK1 deficiency." (PMID 34842598, 2021). "The essentiality of this pathway is underlined by the group of genetic disorders known as galactosemia due to defects on the GALK1, GALT or GALE enzymes." (PMID 27005423, 2016). "Interestingly, this transient fluctuation of Gal-1-P is also observed in GALK1 deficiency and these patterns of galactose and Gal-1-P during the neonatal period are similar for the two types of galactosemia." (PMID 34842598, 2021). "Some of these cases may have also been diagnosed as “transient” unexplained galactosemia or mild GALK1 deficiency based on mildly elevated Gal-1-P during the neonatal period." (PMID 34842598, 2021). "Galactosemia results in the deficiency of enzymes in the Leloir pathway including galactokinase (GALK1), galactose-1-phosphate uridylyltransferase (GALT), galactose mutarotase (GALM), or UDP-galactose 4′-epimerase (GALE), any of which can compromise the metabolism of galactose." (PMID 35118398, 2021). "In addition, we speculate that elevated GALK1 activity could be one of the possible causes for a positive result for galactosemia in newborn screening." (PMID 19309526, 2009). "Other potential therapies focus on influencing the cascade of events in galactosemia and include GALK1 inhibitors, aldose reductase inhibitors, and endoplasmic reticulum stress reducers." (PMID 36615667, 2022). "Type II galactosemia (previously known as galactokinase deficiency; OMIM#230200) is caused by mutations in the gene coding for the enzyme galactokinase (GALK1; EC 2.7.1.6)." (PMID 33562227, 2021). "Deficits in three enzymes in this pathway, namely galactose-1-phosphate uridylyltransferase (GALT), galactokinase (GALK1), and UDP-galactose-4′-epimerase (GALE), are associated with genetic galactosemia." (PMID 34842598, 2021). "We recently identified patients with galactosemia and biallelic variants in GALM, encoding galactose epimerase (GALM), an enzyme that is directly upstream of GALK1." (PMID 34842598, 2021). "In classic galactosemia, GALT enzymatic deficiency causes the accumulationof Gal-1-P, the product of the enzyme galactokinase 1 (GALK1; EC 2.7.1.6)upstream of GALT in the Leloir pathway." (PMID 33724769, 2021). "Focus has been on substrate reduction therapies by targeting GALK1 to decrease galactose-1-phosphate concentrations, and recently superoxide dismutase mimics appear to treat a fruit fly model of galactosemia." (PMID 27005423, 2016). "Previously, we observed elevated GALK1 activity was common in Korean newborns with a positive neonatal screen result for galactosemia." (PMID 19309526, 2009). "Various missense mutations in GALK1, GALT, and GALE genes have been identified in patients with galactosemia." (PMID 19309526, 2009). "Previously, we investigated the phenotypic distribution of 249 Korean patients with a positive newborn screen for galactosemia and found that elevated GALK1 activity was observed frequently in these newborns [authors' unpublished data]." (PMID 19309526, 2009). "Another ongoing therapeutic strategy under study concerns the conversion of classic galactosemia into GALK1 deficiency, a milder form of galactosemia in which patients do not accumulate Gal-1-P." (PMID 28281081, 2017). "However, the fact that patients with GALK1 deficiency experience galactitol accumulation but not the broad range of severe long-term complications of classic galactosemia strongly suggests a limited efficacy of aldose reductase inhibitors." (PMID 28281081, 2017). "Genetic analysis of the galactosemia genes, namely, GALT, GALE, and GALK1, led to the identification of four novel and four rare variants of uncertain significance." (PMID 38090149, 2023).
galactosemia (continued). "Although individuals with elevated GALK1 activity do not have a clinical phenotype of classical galactosemia, the long-term accumulation of toxic galactose 1-phosphate may cause a minor degree of damage to susceptible organs, such as the ovary and brain." (PMID 19309526, 2009).
cataract (10 papers, 2008 to 2024). Partial or complete opacity of the crystalline lens of one or both eyes that decreases visual acuity and eventually results in blindness. "GALK deficiency or galactosemia II (OMIM 230200) is caused by mutations in the GALK1 gene, with its main clinical presentation concerning the formation of cataracts due to galactitol accumulation in the lens." (PMID 38090149, 2023). "In contrast, cataracts are the only consistent symptom in patients with GALK1 deficiency (type II galactosemia)." (PMID 34842598, 2021). "Identification of the pathogenic mutations in GALK1 and the phenotype of cataracts associated with these mutations will increase our understanding of lens biology at a molecular level, which will lead to better treatments and therapeutics." (PMID 20405025, 2010). "In GALK1 deficiency, the neonatal incidence of transaminase elevation, bleeding diathesis, and encephalopathy are higher compared to those in the general population, as well as compared to the incidence of cataracts." (PMID 34842598, 2021). "Stambolian and colleagues first identified mutations in GALK1 in families with cataracts." (PMID 20405025, 2010). "This is similar to what others have reported when observing GALK1 and cataracts in the metabolism pathway." (PMID 34299682, 2021). "Finally, variations in at least eight genes underlying genetic forms of cataract (EPHA2, GJA8, GALT, SLC16A12, HSF4, GALK1, FTL, and CRYAA), and at least 10 other diverse genes have been associated to varying degrees with age-related cataract." (PMID 21042563, 2010). "All affected individuals reported in this study developed cataracts in their infancy whereas the unaffected heterozygous carriers of the pathogenic mutations in GALK1 did not present any signs or symptoms of caractogenesis, even in their forties." (PMID 20405025, 2010).
hepatocellular carcinoma (7 papers, 2009 to 2023). A malignant tumor that arises from hepatocytes. "GALK1 is reported to be a novel candidate therapeutic target for hepatocellular carcinoma as its important role in protein glycosylation." (PMID 34026819, 2021). "The luciferase reporter construct containing -441 to -1 of the GALK1 promoter was able to support the expression of the reporter gene in hepatoma cell lines, HepG2 and Hep3B, suggesting that this region has promoter activity." (PMID 19309526, 2009). "Because of its importance in protein glycosylation, researchers believe that GALK1 could be used as a new valuable therapeutic target for hepatocellular carcinoma." (PMID 36814419, 2023). "Of these 8 kinases, GALK1, PCK1 and PANK1 were highly expressed in normal liver tissues and down-regulated in hepatocellular carcinoma (HCC)." (PMID 35280671, 2022).
galactosemia type 2 (5 papers, 2021 to 2024). "Variants in the GALK1 gene are associated with type 2 galactosemia and, at present, the variant spectrum comprises more than 30 variants." (PMID 35883524, 2022). "GALK1: Homozygous mutations in the galactokinase 1 gene (GALK1) on chromosome 17q were first discovered in families with autosomal recessive galactokinase 1 deficiency with cataract or galactosemia-type 2." (PMID 38927721, 2024). "Mutations in GALK1 can cause GALK deficiency or galactosemia type 2." (PMID 33545950, 2021).
Bladder Cancer (4 papers, 2021 to 2026). "In this study, we established the GMII consisting of eight glutamine metabolism-related genes (ENPP1, GALK1, TALDO1, CYP19A1, FASN, AHCY, SLC7A9, and HSPG2), a high value of which is associated with poor prognosis in bladder cancer patients." (PMID 36911676, 2023). "The expression of five of the eight GMII genes (TALDO1, AHCY, FASN, GALK1 and SLC7A9) in bladder cancer tissues was higher than that in normal tissues, while ENPP1, CYP19A1 and HSPG2 were down-regulated in tumor tissues (p < 0.05)." (PMID 36911676, 2023). "In this study, we selected four hypoxia-related genes that were highly related to bladder cancer patients’ survival status, including ANXA2, GALK1, COL5A1, and HS3ST1, to construct a signature and this signature is independent of other clinical characteristics." (PMID 34026819, 2021). "No research on the relationship between GALK1 and bladder cancer has been found yet." (PMID 34026819, 2021).
Age-related cataract (3 papers, 2008 to 2022). A type of cataract (opacification of the lens) that forms during the course of aging. "At least 8 genes are known to be directly associated with age-related cataracts, including EPHA2, GJA8, GALT, SLC16A12, HSF4, GALK1, FTL, and CRYAA." (PMID 36107580, 2022).
colorectal cancer (3 papers, 2021 to 2024). A primary or metastatic malignant neoplasm that affects the colon or rectum. "Our study suggests that GALK1 may be regulated by colorectal-cancer-specific enhancers and be associated with the progression of colorectal cancer." (PMID 34361106, 2021). "Moreover, the expression level of GALK1 (the enzyme that converts galactose to galactose-1-phosphate) was shown to correlate with poor prognosis in glioblastoma as well as in colorectal cancer." (PMID 39518017, 2024). "Moreover, GALK1 has also been implicated in promoting high epithelial–mesenchymal transition (EMT) and worse OS in colorectal cancer (CRC)." (PMID 37760606, 2023). "This may have been due to the long-range interactions between the colorectal-cancer-specific enhancer and GALK1 (~45 kb)." (PMID 34361106, 2021). "However, few studies have reported the function of GALK1 in colorectal cancer until now." (PMID 34361106, 2021).
chronic cystitis (2 papers, 2016 to 2023). Recurrent infections of the urinary bladder. "First, validation of NNMT, GALK1, and HTRA1 and other candidates tightly correlated with BCa stage needs to be performed using larger patient cohorts of BCa including benign conditions such as cystitis, samples with hematuria, as well as other tumors from the urogenital tract (prostate, and renal)." (PMID 37834386, 2023).
congenital cataracts (2 papers, 2008 to 2010). "Here, we report pathogenic mutations in GALK1 that are responsible for autosomal recessive congenital cataracts in two Pakistani families." (PMID 20405025, 2010). "This is the first report associating GALK1 with autosomal recessive congenital cataracts in families of Pakistani origin." (PMID 20405025, 2010). "Here, we report pathogenic mutations in GALK1 that are responsible for autosomal recessive congenital cataracts in consanguineous Pakistani families." (PMID 20405025, 2010).
Encephalopathy (2 papers, 2021 to 2022). Encephalopathy is a term that means brain disease, damage, or malfunction. "Recently, bleeding diathesis, encephalopathy, and an elevation of transaminase during the neonatal period have been reported to be associated with GALK1 deficiency." (PMID 34842598, 2021). "According to recently published data, the phenotypic manifestations of GALK1 deficiency may also include an increase in transaminases during the neonatal period, bleeding diathesis, and encephalopathy." (PMID 36615667, 2022).
glioblastoma (2 papers, 2023 to 2024). The most malignant astrocytic tumor (WHO grade IV). "In the Leloir pathway, galactose is initially converted to galactose-1-phosphate by galactokinase (GALK1), which allows cancer cells to utilize galactose as an alternative fuel source instead of glucose in glioblastoma (GBM)." (PMID 37760606, 2023).
liver cancer (2 papers, 2023). An epithelial or non-epithelial malignant neoplasm that arises from the liver. "GALK1’s relation with cancer was first observed by Barretina and co-workers who reported that the GALK1 gene was up-regulated by at least six-fold in 28 different human liver cancer cell lines." (PMID 37834386, 2023). "In addition, GALK1 could be a new therapeutic target for liver cancer treatment." (PMID 37273920, 2023).
autoimmune disease (1 paper, 2024). A disorder resulting from loss of function or tissue destruction of an organ or multiple organs, arising from humoral or cellular immune responses of the individual to their own tissue constituents. "IL1RL2, IL6R, ERBB3, ICAM1, IL1R1, and GALK1 were also enriched in categories like immune system disease, autoimmune disease, skin disease, and disease of anatomical entity." (PMID 38773393, 2024).
bladder tumors (1 paper, 2026). "Analysis of the TCGA data revealed that the enzyme galactokinase-1 (GALK1) is overexpressed (p < 0.0001) in bladder tumors compared to normal tissue." (PMID 41898771, 2026). "Our data also confirmed GALK1 protein upregulation in multiple human BCa cell lines and rodent bladder tumors." (PMID 41898771, 2026).
dementia (1 paper, 2025). Loss of intellectual abilities interfering with an individual's social and occupational functions. "GALK1, EPHB4, and NOS3 showed significant region-dependent differential expression, with higher expression in the DLPFC of dementia cases and more pronounced regional differences compared to controls." (PMID 40799764, 2025).
hyperferritinemia (1 paper, 2010). "Other known causes of congenital, hereditary cataracts are mutations affecting enzymes of sugar metabolism (e.g. galactokinase 1, GALK1) or other metabolic disorders like hyperferritinemia (FTL)." (PMID 21031021, 2010).
Hyperglycemia (1 paper, 2013). An increased concentration of glucose in the blood. "Several carbohydrate metabolism genes involved in metabolism of monosaccharide and carbohydrate and hyperglycemia (e.g. CPT1A, GALK1, INS, LEPR, PRLR and SCD) are highly expressed in mouse CPE and only lowly in human CPE." (PMID 24391755, 2013).
leukaemia (1 paper, 2024). "In addition, we also found some leukaemia‐specific proteins, oncogenes (COL2A1, CLIP1, NUMA1 and GALK1), and stem cell‐regulated proteins (ACAN, VCAN, COMP and PRDX6)." (PMID 38499475, 2024).
Renal glucosuria (1 paper, 2011). "Other examples where early onset cataract is the major manifestation of an underlying systemic disorder include renal glucosuria due to solute carrier family 16, member 12 (monocarboxylic acid transporter 12; SLC16A12) mutations, and lactose intolerance due to galactokinase 1 (GALK1) mutations." (PMID 21541272, 2011).
Retinal atrophy (1 paper, 2007). A nonspecific term denoting wasting, especially as a result of degeneration, of the retinal pigment epithelium (RPE) and neurosensory retinal cells. "The locus for progressive rod-cone degeneration is known to be close to the GALK1 locus, on the telomeric region of chromosome 9, where the retinal atrophy locus of the Finnish lapphund has been mapped." (PMID 17623091, 2007).
retinal disease (1 paper, 2007). "This could imply that there have been recombination events between GALK1 and the PRA locus in this breed, or that the retinal disease is a different one." (PMID 17623091, 2007).
retinoblastoma (1 paper, 2022). A malignant tumor that originates in the nuclear layer of the retina. "Retinoblastoma-derived exosomes are enriched in multiple metabolic enzymes, including enolase 3 (ENO3), galactokinase-1 (GALK1), asparagine synthase (ASNS) and saccharopine dehydrogenase (SCCPDH)." (PMID 36588730, 2022).
cancer (3 papers, 2022 to 2023). A tumor composed of atypical neoplastic, often pleomorphic cells that invade other tissues. "Out of these, and based on the available literature data about their involvement in cancer and BCa, and positive correlation with stage, we have preselected NNMT, GALK1, and HTRA1 to be further tested in urine samples." (PMID 37834386, 2023). "However, the specific roles of SEC13, ALG1, FAM162A, GALK1, and XYLT2 in cancer remain unclear." (PMID 35963622, 2022).
GALK1 also shares sentences with these, for which no sentence is quoted: infection (5 papers); tumor (4); COVID-19 (2); Blindness (1); breast carcinoma (1); cystinuria (1); cystitis (1); glioma (1); immune system disease (1); melanoma (1); metabolic disorders (1); rod-cone degeneration (1); Sepsis (1); tyrosinemia (1); virus infection (1).